CD4 (CD4 molecule)
Diseases named in the same sentence as CD4 in open-access papers (continued):
Sharing a sentence is not in itself a finding about the gene and the disease.
infection (continued). "HIV targets AT both directly (direct infection of AT CD4 T cells) and indirectly (viral protein release, inflammatory signals, and gut disruption)." (PMID 34220817, 2021). "During P. yoelii lethal (17XL) infection, the decrease of DP and CD4+ SP thymocytes, the reduced proliferation of DP thymocytes and the downregulation of CD8 expression on the thymic T-cell subpopulations were observed." (PMID 34113341, 2021). "To test this, we depleted CD4+ T cells beginning at day 7 after infection, which should allow CD8+ T cells to be primed in the presence of CD4+ T cell help." (PMID 33508041, 2021). "While our study does not rule out a contribution of other cell types, especially γδ T cells, our findings suggest that CD4 T cells are the primary source of IL-17, especially during re-infection of convalescent mice." (PMID 33976385, 2021). "In vivo and in vitro studies of S mansoni‐infected mice demonstrated the recruitment of SEA‐sensitive splenic CD4+ T lymphocytes that were retained in the granuloma and subsequently migrated into the circulation as the infection developed." (PMID 32692855, 2021). "Consistent with this, we observed a stark increase in the number of tongue CD4+ T cells upon re-infection, most of which expressed high levels of CD103, and this was largely independent of FTY720." (PMID 32719409, 2021). "From the secondary lymphoid organs where they were activated, CD8+ and CD4+ T cells disperse in the body and accumulate at the site of infection." (PMID 34946179, 2021). "At 4, 8-, and 48-weeks post-infection, CD4 T cells that proliferate and produce IFN-γ to antigen stimulation comprise approximately 8.19, 11.91, and 9.74% of the total CD4 response, respectively (pie charts, green color)." (PMID 34336973, 2021). "In summary, these studies show, by both cytokine production pattern and expression of differentiation markers, that MPT70-specific CD4 T cells are maintained at a lower state of differentiation throughout infection compared to ESAT-6-induced T cells." (PMID 33879592, 2021). "Cellular immune responses can be broad but vary widely, and lymphopenia is a prominent feature of more severe infection, affecting CD4+ and CD8+ T cells, as well as B cells." (PMID 33533915, 2021). "In line with the in vitro results, TIM-3 surface protein expression in effector-memory T helper cells (CD4+CD62LloCD44hi), which is the population primed and expanded during infection, was progressively increasing over time." (PMID 34108960, 2021). "Pseudoviruses made with the envelopes of JRFL and NL43 established infection exclusively on R5 and X4-expressing U87.CD4+ cells, respectively, confirming the validity of this phenotypic co-receptor tropism assay." (PMID 34305873, 2021). "We therefore directly compared the frequency of SARS-CoV-2-specific memory CD4+ T-cell subsets at three months after infection and vaccination." (PMID 34960185, 2021). "Although microglia and macrophages in the CNS express low levels of CCR5 and CD4, and the infection of these cells in uncommon, infection has been demonstrated in vitro and in vivo." (PMID 34960781, 2021). "The median CD4+ cell count in the group of patients with double infection was 114 cells/mm3, and the viral load was 6.8 log10 copies/mL." (PMID 34835417, 2021). "Removal of convalescent outlier PID4112 revealed the magnitude of the spike-specific CD4+ T cell response to be lower in the convalescents than in infection-naïve participants after full vaccination." (PMID 34636722, 2021). "Patients who experienced an infection had significant higher frequencies of EM CD4+ and TEMRA CD8+ cells, and also significantly (p = 0.003) increased percentages of ABCs after transplantation, which was not seen in patients who did not." (PMID 34749733, 2021).
infection (continued). "We therefore performed a detailed genetic analysis of HIV-1 proviral DNA sequences derived from a broad range of peripheral blood CD4+ T-cell subsets with measured cellular half-lives from participants who initiated ART during early or late infection." (PMID 34544282, 2021). "Thereby numbers of CD4+ T cells in the mesLN increased during infection in BALB/c (average number: 1.0 × 107 cells) and C57BL/6 mice (5.5 × 106 cells) and by trend (p = 0.1) in F1 mice (average number: 7.9 × 106 cells)." (PMID 33452272, 2021). "This process causes the secretion of pro-inflammatory cytokines such as IL-1β, which create a heightened inflammatory state, recruiting more CD4 T cells to the sites of inflammation, increasing infection and cell death." (PMID 33542308, 2021). "By contrast, infection through the rectal mucosa, which contains many resident CD4+ T cells can be protected by the antiviral properties of IFN-I." (PMID 34512664, 2021). "For example, both CD4+ T lymphocytes and B lymphocytes are required to control infection with B. melitensis in mice following i.p. inoculation while only α/β T lymphocytes (either CD4+ or CD8+) are required for control following intranasal infection." (PMID 34335551, 2021). "The results of this study highlight the differential impact of TCR signal strength in shaping CD4 T cell fate according to the infection context." (PMID 33684030, 2021). "(B) The proportions of Tfh and Treg among spike-specific CD4+ T cells are similar in infection-naïve vs. convalescent individuals after vaccination." (PMID 34636722, 2021). "Infection generated a broadly reactive and clonally diverse CD4+ T cell response with the most prevalent clonotypes and predicted antigen specificities residing in both the lung and lung-draining lymph nodes." (PMID 34106992, 2021). "The resulting life-long infection can be reactivated from latency to a productive lytic state from latently infected and transformed CD4+ T cells." (PMID 35056456, 2021). "Quantitatively, the memory response is skewed toward more CD4/helper T cells than CD8/cytotoxic T cells despite their often equivalent frequencies immediately after infection." (PMID 34471260, 2021). "Upon depletion of CD4+ cells, we observed decreased levels of serum IgA after infection in both NM and DM mice, potentially indicating decreased seroconversion." (PMID 34877500, 2021). "CD4+ T cells and CD8+ T cells from both WT and TLR7 KO mice expressed higher levels of activation-associated molecules after infection for 6 weeks (P < 0.05)." (PMID 34692568, 2021). "We described an enhanced compensatory CD4+ T cell effector function in TKO mice with increased IFNγ release during the course of infection." (PMID 33968021, 2021). "CD4 counts declined approximately linearly, but slopes decreased gradually as infection duration increased." (PMID 34546644, 2021). "Overall, our results show the induction of a strong CD4+ T-cell response after STM infection, both locally and systemically." (PMID 34451970, 2021). "CD4+ T cells were either unstimulated or activated with anti-CD3/anti-CD28 beads prior to infection with HIV-1VSVgNL4-3, whereas monocyte derived macrophages (MDMs) were infected with R5-tropic HIV-1NL4-3 BaL." (PMID 34962974, 2021). "In the current study, we characterized the interactions among Ly6C+ monocytes, Ly6C− monocytes, and CD4+ T cells in the context of IL-27 signaling in a mouse model of infection with African trypanosomes." (PMID 33593983, 2021). "Strikingly, the proportion of CD4 EM T cells expressing PD-1 was increased in primary infection and remained almost unchanged even three years after ART initiation." (PMID 34149690, 2021). "Like CD4, NBD-556 binding to gp120 can trigger conformational changes and formation of the CCR5 binding site, and thus enhancing the infection to CD4-/CCR5+ cells." (PMID 33922579, 2021).
infection (continued). "In a previous study, we have shown the induction of multifunctional STM-specific CD4+ T cells after vaccinating pigs two times with Salmoporc followed by an infection with STM." (PMID 34451970, 2021). "It was demonstrated that pretreatment of HIV strains with cathepsin D not only enhanced infection of CD4+ T-lymphocytes but also allowed infection of epithelial CD4-negative cells." (PMID 34421929, 2021). "Of note, CD4+ T cells contributed to the maintenance of stable colonization with C. albicans in experimentally infected mice also beyond the first 2 weeks of infection." (PMID 32719409, 2021). "Infection of an eGFP.OR3 expressing SupT1 cell line or of primary activated CD4+ T cells transduced to express eGFP.OR3 with NNHIV ANCH showed nuclear OR3 punctae and separation of IN-FP and OR3 punctae as observed for TZM-bl cells." (PMID 33904396, 2021). "These outcomes were related to smaller numbers of IFN-γ and TNF-α T CD4 producing cells at the site of infection." (PMID 34745100, 2021). "Overall, these results demonstrate that endogenous HA produced by HAS2 in fSFs limits the fibroblasts’ ability to enhance infection of CD4+ T cells by HIV." (PMID 33976386, 2021). "Further, CD4+ T cell and NK cell cytopenia are recognized as characteristics of infection by SARS-CoV-2." (PMID 33602326, 2021). "Here, we measured cellular infection in CSF during early acute infection directly ex vivo and observed widespread CD4+ T cell infection in all six PLWH and the majority of macaques, including evidence of active viral replication." (PMID 34874976, 2021). "No clear FcγRIIa-H131R and FcγRIIIa-V176F association with time to HIV-1 acquisition, viral load in early infection, or CD4+ T-cell decline over time after infection." (PMID 34017334, 2021). "On the contrary, the low dose infected macaques demonstrated an early TNF-α response in the Mtb-specific CD4+ T cells at weeks 1 which decreased at week 3 post-infection." (PMID 34484203, 2021). "The inhibition of CD4+ T cell trans-infection involves the blocking of HIV-1 capture and transfer through an interaction between the BmA and dendritic cells, thus, preventing the virus from interacting with dendritic cells." (PMID 34603287, 2021). "In fact, CCR5-utilization is more relevant for macrophages which express high levels of CCR5, as compared to CD4+ T cells, but macrophages express low levels of CD4 and so are more relevant later on in infection when CD4+ T cells are depleted." (PMID 35126374, 2021). "The median CD4 count at seroconversion for persons aged 15–24 was estimated to be 579 cells/mm3 [95% credible interval (CrI): 570–589] and would decline to zero CD4 cells/mm3 23 years (95% CrI: 21.5–24.4) after infection." (PMID 34546644, 2021). "We conclude that infection of T. brucei leads to depletion and repopulation of liver macrophages, associated with a substantial influx of CXCR6+CD4+ T cells that mediates mortality." (PMID 34614031, 2021). "CD4+ T cells (10x106) were adoptively transferred into γ-irradiated (sub-lethal dose of 800 rads/mice) Thy1.1 congenic animals followed by infection with an aerosol challenge of M. tb H37Rv." (PMID 34415976, 2021). "A second Sp19F infection at day 7; however, elicited rapid recruitment of all conventional CD4+ T cell subsets including naïve T (TNaive), central memory T (TCM), effector memory T (TEM), and effector T (Teff) cells." (PMID 34611166, 2021). "Though Foxp3+ Treg expansion has been observed in the mLN of S. ratti-infected mice, we did not observe increased frequencies of polyclonal Foxp3+ and Foxp3+GATA3+ CD4+ T cells in the lungs of mice 14 days post S. ratti-infection relative to naïve mice." (PMID 34237106, 2021). "Compared with the Nc (normal control) group, TIGIT expression on splenic CD4+ T cells of mice was significantly upregulated from the 1st week after PRU cyst infection to the 12th week after infection (p < 0.01)." (PMID 34421855, 2021).
infection (continued). "In order to assess the impact of depleting CD4 T cells from the nasal cavity on the course of infection, we assessed CFU counts in the nose." (PMID 33976385, 2021). "This contrasts with the immune suppressive profile during infection such as antigen specific hypo-responsiveness, T cell memory pool distortion and increased CD4+CD25+FOXP3+T cell numbers." (PMID 33746974, 2021). "Detection of Spike-specific memory CD4+ T cells several months after infection is encouraging for the efforts focusing on SARS-CoV-2 Spike protein as a vaccine candidate." (PMID 33777028, 2021). "HIV attacks and destroys the immune system ́s CD4 cells which are the major infection fighting cells in the body." (PMID 34046145, 2021). "This in vivo study showed that P-selectin binding in CD4+ T cells occurs early during the immune response and persists to late timepoints after infection, when these cells differentiate to form memory T cells." (PMID 33708224, 2021). "In the early stage of infection, CD4+ regulatory T cells are essential for activating CD8+ T cells to respond to acute respiratory virus infection." (PMID 33664741, 2021). "In contrast, delaying depletion of CD4+ T cells until day 7 after infection significantly increased the frequency and number of functional CD8+ T cells." (PMID 33508041, 2021). "Induction of STM-specific IL-17A single-producing, IFN-γ/IL-17A co-producing, TNF-α/IL-17A co-producing and IFN-γ/TNF-α/IL-17A triple-producing CD4+ T cells mainly took place after infection with highest levels reached in INF animals." (PMID 34451970, 2021). "This amplified enhancement required direct contact between the fibroblasts and CD4+ T cells, and could be attributed to both increased rates of trans-infection and the increased ability of HA-deficient fibroblasts to push CD4+ T cells into a state of higher permissivity to infection." (PMID 33976386, 2021). "For example, infection of mice with Leishmania major helped define the factors driving CD4 Th1 and CD4 Th2 cell development and maintenance." (PMID 33841444, 2021). "Taken together, our results suggest that CD4+ T cells demonstrate a switch-like behavior in response to infection." (PMID 34343169, 2021). "HIV (R5-tropic strain) infection of macrophages requires two key entry receptors (CD4 and CCR5) on the cell surfaces." (PMID 34356516, 2021). "This was due, at least in part, to an unexpected need for CD4+ T cell help for CD8+ T cells after i.n. infection." (PMID 33508041, 2021). "Both the number and proportion of CD4 T-cells were significantly higher compared to CD8 T-cells throughout the course of the infection." (PMID 35186781, 2021). "We reported that all the cells infected in the intestine in very early SIV infection were CD4+CD69+ cells and that the selective loss of CD69+ cells occurred in the blood in very early infection." (PMID 34960667, 2021). "The stage of infection, which presents different phases, can be determined by measuring the CD4+ T‐cell counts and the viral load of the patients." (PMID 33792105, 2021). "We examined the cellular sources of IL-17 in the nasal cavity of B. pertussis infected mice and revealed that CD4 cells were the dominant source of IL-17 by day 10 of primary infection and in convalescent mice." (PMID 33976385, 2021). "Upon successful infection of individual activated target CD4+ T-cells, the majority of the infecting viruses undergo functional decay before or during the reverse transcription step." (PMID 33918134, 2021). "In this same model of infection, cd4-/- animals showed improvement in joint swelling, thus confirming the need for CD4 T cells in this process." (PMID 34064728, 2021). "To study transcriptomic profiles upon infection, we used microarray and RNA‐Seq data sets generated in primary CD4+ T cells infected with HIV‐1pNL4‐3." (PMID 34289240, 2021).
infection (continued). "Even though during the natural course of infection, there are many other viral/host factors directing the type of effector responses, our results show that rNP alone induces CD4+ T cell response and sufficient to drive this response towards Th1." (PMID 34851958, 2021). "Following M. tuberculosis infection, there was an influx of CD4+ T cells into the lungs that peaked at 4 weeks post-infection (p.i.)and was sustained for 20 weeks." (PMID 34793507, 2021). "Because CD4+ T cells are among the most significant cells that will secrete cytokines, and hMPV leads to a proinflammatory environment upon infection, it is relevant to evaluate this secretion." (PMID 33809875, 2021). "Already at day 3 post a second infection SC animals showed increased numbers of CD4 T cells, and more Cyt+ CD4 T cells in the GT (compared to after the first infection)." (PMID 34925371, 2021). "The precise location of this latently-infected reservoir is debated, but is likely distributed across a number of CD4 T cell subsets, including long-lived memory cells, thereby explaining the long persistence of infection." (PMID 33635929, 2021). "Although we expect that the infected rate of any cellular factor would correlate with the infection rate of the total CD4 population, this correlation would result in a slope of 1 if the infected subset is just a subsample of the total infected pool." (PMID 34228640, 2021). "To do this, we infected mice and induced IL-10 overexpression starting at day 5 after infection (as above) and analyzed the kinetics of the CD4+ T cell response in the lungs." (PMID 34554927, 2021). "In human leprosy, intradermal IFNγ administration has been shown to change local infection from lepromatous to tuberculoid leprosy, with increases in the numbers of CD4+ T-cells and reductions in bacterial numbers in dermal biopsies." (PMID 34684248, 2021). "Treg cells accounted for only 0.7% of CD4+ T cells in the uninfected group, but increased to 12.3% at 3 weeks post-infection, and began to decrease at 4 weeks post-infection." (PMID 33959105, 2021). "Assessment of T cell responses demonstrated a net decrease in naive CD4+ T cell frequencies at day 1 and day 7 post infection, while CD8+ T cell frequencies remained unchanged." (PMID 34494025, 2021). "We profiled longitudinal genome-wide DNA methylation in monocytes and CD4+ T lymphocytes from 22 participants in the RV254/SEARCH010 acute HIV infection (AHI) cohort that diagnoses infection within weeks after estimated exposure and immediately initiates ART." (PMID 34388205, 2021). "We observed increased numbers of CCR7+ and CD62L+ CD4+ T cells in anti-CD300a antibodies treated mice, which was significant at the later stages of infection (D14 and D21)." (PMID 35116028, 2021). "Viral competition analysis revealed that Envchronic viruses resided and replicated mainly in the tissue, while Envacute viruses penetrated the human tissue and established infection of CD4+ T cells more efficiently." (PMID 33177204, 2021). "Following antigen stimulation, we observed a significant increase in the frequency of proliferating CD4 T cells from M. bovis-infected animals as compared to controls at 4, 8-, and 48-weeks post-infection." (PMID 34336973, 2021). "Altogether, these data show that the TH1 cells are the predominant CD4 T-cell subset produced during persistent UgCl223 infection, but IFNγ production by these TH1 cells is impaired." (PMID 35186781, 2021). "PECs from STAT1+/+ mice recruited acutely during infection with this helminth significantly inhibited the proliferative response of both CD4+ and CD8+ splenocytes, reducing this response by at least 50%." (PMID 34684235, 2021). "Over years of research, we have demonstrated that low levels of antigens captured by B cells during the resolution of an infection render antigen experienced CD4 T cells into a quiescent/resting state." (PMID 34177919, 2021).